SKINT1L (Skint1 like (pseudogene))
Synonyms: SKINT1LP; BTN12; formerly SKINTP; SKINTL
Gene: Transcribed unprocessed pseudogene on chromosome 1 (48,161,799 to 48,179,230, reverse strand). Ensembl gene ENSG00000242267.
Diseases named in the same sentence as SKINT1L in open-access papers:
SKINT1L is named in the same sentence as 4 diseases in open-access papers, as found by Europe PMC text mining. Sharing a sentence is not in itself a finding about the gene and the disease.
SKINT1L shares sentences with these, for which no sentence is quoted: tumor (2 papers); breast carcinoma (1); cancer (1); malignant melanoma (1).